AQP9 (aquaporin 9)
Diseases named in the same sentence as AQP9 in open-access papers (continued):
Sharing a sentence is not in itself a finding about the gene and the disease.
colorectal cancer (19 papers, 2015 to 2026). A primary or metastatic malignant neoplasm that affects the colon or rectum. "Upregulation of AQP9 is also associated with increased sensitivity of colorectal cancer cells to treatment with 5-florouracil (5-FU) through increased uptake of 5-FU." (PMID 38136293, 2023). "5-FU chemotherapy possesses a better curative effect in mice with colorectal cancer because of cell cycle arrest caused by AQP9." (PMID 35972604, 2022). "AQP1, AQP3, AQP5, and AQP9 are associated with colorectal cancers; among them, it has been indicated that AQP5 promotes the proliferation and metastasis of CRC; moreover, elevated expression of AQP5 in CRC tissue is associated with a poor prognosis of colorectal cancer." (PMID 36114463, 2022). "AQP1, AQP3, AQP5, and AQP9 all have roles associated with colorectal cancer." (PMID 30555637, 2018). "Colorectal cancer patients with high AQP9 expression exhibited favorable disease-free survival compared to those with its low expression." (PMID 35477402, 2022). "In colorectal cancer, AQP9-mediated cell cycle arrest was correlated to RAS activation as well as improved chemosensitivity to 5-fluorouracil (5-FU)." (PMID 35477402, 2022). "Within this final set, the largest proportion of studies addressed AQP1, followed by AQP5, AQP4, AQP3 and AQP9, for a diverse array of cancer types, including brain, lung, breast and colorectal cancers." (PMID 32679804, 2020). "AQP5 and AQP9 are potential targets to increase the effectiveness of chemotherapeutic drugs among colorectal cancer patients." (PMID 30555637, 2018). "AQP1, AQP3, AQP5, AQP8 and AQP9 play a clinically relevant role in hepatic cancer as they do in colorectal cancer." (PMID 30555637, 2018). "Moreover, AQP9 expression is involved in colorectal cancer and is considered a predictive biomarker for chemotherapy response." (PMID 36983834, 2023). "However, high expression levels of AQP9 in gastric cancer and colorectal cancer patients were correlated with better OS." (PMID 33643388, 2021). "Furthermore, one cohort (GSE17536) revealed that high AQP9 expression predicted worse prognosis for colorectal cancer patients." (PMID 33247170, 2020). "In addition, AQP9 was recently shown to enhance the cytotoxic effect of nucleoside analogs in colorectal cancer, and could thereby be used as a novel predictor for the benefit of nucleoside analog chemotherapy in the disease." (PMID 30042691, 2018). "AQP9 is also considered to be a potential predictive marker for response to chemotherapy, as non-responsive patients with stage III colorectal cancer also had lower AQP9 gene expression." (PMID 38136293, 2023). "The expression of AQP9 at a low level in patients with stage III colorectal cancer who do not respond to chemotherapy, makes AQP9 a potential prognostic indicator." (PMID 35972604, 2022). "Lower AQP9 expression has been related with non-response to adjuvant chemotherapy, comprising amongst others a nucleoside analog, in colorectal cancer." (PMID 30042691, 2018). "Down-expression of AQP9 was related with non-responses of colorectal cancer cells to adjuvant chemotherapy." (PMID 25886458, 2015). "Conversely, AQP9 might inhibit the invasion of liver cancer cells and the proliferation of xenograft tumors, and also activates RAS signal and sensitize tumor cells to chemotherapy in colorectal cancer." (PMID 34012923, 2021). "However, the role of AQP9 in regulating tumor sensitivity to adjuvant chemotherapy in colorectal cancer (CRC) has not been elucidated." (PMID 28640255, 2017).
Sepsis (16 papers, 2018 to 2025). Sepsis is defined as life-threatening organ dysfunction caused by a dysregulated host response to infection. "An AQP3 increase in macrophages is associated with survival, while AQP9 in neutrophils is inhibited during a prolonged inflammatory state and its expression was considered an independent risk factor for sepsis lethality." (PMID 39125952, 2024). "In this study, we showed that increased AQP9 mRNA expression is an independent risk factor for 30-day lethality in sepsis." (PMID 38279209, 2024). "In the current study we thus asked if loss of Aqp9 function can confer a net protective effect in a model of sepsis where a bacterial infection is present." (PMID 35774785, 2022). "The neutrophil AQP9 expression was considered an independent risk factor for sepsis lethality." (PMID 40558507, 2025). "AQP9 plays a regulatory role in neutrophil migration and is associated with sepsis survival." (PMID 39544938, 2024). "Therefore, this provides a good indication that pre-treatment with AQP9 reduced the rise in ALT caused by sepsis and hence, liver injury." (PMID 35774785, 2022). "Furthermore, AQP9 expression was an independent risk factor for sepsis lethality." (PMID 38279209, 2024). "With the help of these inhibitors, and by using Aqp9-/- knockout mice, we showed the important roles for AQP9 in murine models of endotoxemia and polymicrobial sepsis and systemic inflammation." (PMID 40558507, 2025). "Specific inhibitors such as HTS13286 and RG100204 targeting AQP9 have demonstrated promise in reducing inflammation, improving survival, and mitigating organ dysfunction in sepsis models." (PMID 39544938, 2024). "RG100204 significantly reduced cardiac dysfunction even when administered 3 hours after the onset of sepsis, highlighting AQP9 as a promising drug target for the treatment of sepsis-induced cardiac dysfunction." (PMID 39544938, 2024). "RG100204 reduced cardiac and renal dysfunction, decreased activation of the NLRP3 inflammasome pathway and reduced myeloperoxidase activity in lung tissue, suggesting that AQP9 is a potential drug target for polymicrobial sepsis." (PMID 39544938, 2024). "In vitro studies have shown that inhibition of AQP9 with phloretin can reduce mortality, inflammatory responses and organ damage in sepsis models." (PMID 39544938, 2024). "Recently, AQP3 and AQP9, the most representative AQPs in macrophages and neutrophils, respectively, were shown to respond differently in the sepsis clinical condition." (PMID 39125952, 2024). "Another point of contact between ROS and NLRP3 has been recently reported in LPS-induced sepsis, using a specific inhibitor for aquaporin 9 (AQP9)." (PMID 37507935, 2023). "In this study, we report that CLP mice subjected to polymicrobial sepsis have increased translocation of p65 in both the heart and kidneys which is attenuated by post-treatment with the AQP9 inhibitor RG100204." (PMID 35774785, 2022). "These are warranted to gain a better insight into the effects of AQP9 inhibition on renal dysfunction in sepsis." (PMID 35774785, 2022). "Gene deletion of the neutral solute channel Aquaporin 9 (AQP9) normalizes oxidative stress and improves survival in a bacterial endotoxin induced mouse model of sepsis." (PMID 35774785, 2022). "A recent study demonstrated improved survival of Aqp9-/- knockout mice in an LPS induced mouse model of sepsis." (PMID 35774785, 2022). "Several studies showed that AQP3 is essential for T cell function and macrophage migration and that AQP5 and AQP9 regulate neutrophil cell migration and impact sepsis survival." (PMID 29449936, 2018). "High levels of AQP3 were associated with augmented survival, whereas AQP9 did not appear to change during sepsis when normalized against the neutrophil count, and a low expression of AQP9 was associated with increased survival." (PMID 40558507, 2025).
Sepsis (continued). "Taken together, these results indicate that AQP9 or AQP3 could be novel drug targets in polymicrobial sepsis and valuable biomarkers of this worrisome condition." (PMID 38279209, 2024). "AQP9 regulates neutrophil migration and affects sepsis survival In leukocytes, AQP9 is located at the cell edge and is thought to be involved in motility, lamellipodium extension and stabilisation, and changes in cell volume that facilitate migration towards chemoattractants." (PMID 39544938, 2024). "In addition, some animal studies regarding the impact of AQP9 on the pathomechnism of sepsis have been conducted." (PMID 38279209, 2024). "The main finding of our study is the correlation between AQP3 and AQP9 expression and sepsis survival at day 8, suggesting AQP modulation might be a promising therapeutical approach during sepsis." (PMID 38279209, 2024). "In contrast, AQP9 expression was not altered during sepsis, and low levels were associated with increased survival." (PMID 39768394, 2024). "In conclusion, AQP3 and AQP9 may play contrary roles in the pathophysiology of sepsis, and these results suggest that AQP9 may be a novel drug target in sepsis and, concurrently, a valuable biomarker of the disease." (PMID 38279209, 2024). "However, in contrast to AQP3, the expression of which increases over the duration of sepsis, AQP9 expression seems to be unaltered." (PMID 38279209, 2024). "AQP9 in M49 can regulate neutrophil cell migration and impact sepsis survival." (PMID 38071387, 2023). "Indeed, the administration of the specific AQP9 inhibitor protects animals from sepsis-induced multiorgan dysfunction." (PMID 37507935, 2023). "Thus, we utilized RG10024 to further interrogate the potential of AQP9 as a drug target in polymicrobial sepsis." (PMID 35774785, 2022). "Since AQP9 plays a role in metabolism and inflammation, it may also play a role in the progression of sepsis." (PMID 35774785, 2022). "Together, these results indicated that AQP9 may be a novel drug target in polymicrobial sepsis and, at the same time, a valuable biomarker of this worrisome condition." (PMID 35883453, 2022). "AQP9 regulates neutrophil cell migration and impacts sepsis survival." (PMID 35883453, 2022). "Indeed, a recent study points towards a role for AQP9 in the pathophysiology of sepsis: when compared to wild-type mice, Aqp9-/- knockout mice challenged with a lethal dose of LPS had a longer survival time and 25% of these mice recovered fully." (PMID 35774785, 2022). "What then is the evidence that inhibition of AQP9 exerts beneficial effects in sepsis?" (PMID 35774785, 2022). "Immune cell migration is an important mechanism that occurs in sepsis and another potential mechanism linking AQP9 to survival in sepsis may relate to the suggested implication of this AQP in neutrophil cell migration." (PMID 33670755, 2021). "Thus, the roles of AQP3 and AQP9 differ in the pathophysiology of sepsis and may be useful biomarkers for sepsis." (PMID 39768394, 2024). "In a murine LPS-induced endotoxic shock model, the AQP9-knockout (KO) mice exhibited longer survival times and decreased inflammation compared to wild-type (WT) mice, highlighting the potential of AQP9 as a promising target for the development of new therapies against sepsis." (PMID 39768394, 2024). "Taken together our findings suggests that AQP9 inhibitors may hold promise for the use in sepsis." (PMID 35774785, 2022). "Nevertheless, detection of AQP9 alone or combined with other biomarkers improving their accuracy, particularly for early diagnosis, may contribute to an increased survival rate in diseases such as cancer and sepsis." (PMID 35883453, 2022). "Together these results indicate that AQP9 may be a novel drug target in polymicrobial sepsis." (PMID 35774785, 2022). "Recent studies suggest that AQPs, particularly aquaglyceroporins like AQP3, AQP7, AQP9, and AQP10, play pivotal roles in immune cell metabolism and offer new therapeutic avenues for sepsis treatment." (PMID 39544938, 2024).
Sepsis (continued). "In sepsis, AQP1, AQP4, AQP5, and AQP9 have been shown to significantly affect organs like the brain, heart, lungs, kidneys, and liver." (PMID 39544938, 2024). "In a study, the novel AQP9 inhibitor RG100204 was shown to normalise oxidative stress and improve survival in mouse models of sepsis." (PMID 39544938, 2024). "The novel AQP9 inhibitor RG100204 showed reduced septic cardiomyopathy and multi-organ failure in a murine CLP model of polymicrobial sepsis by improving outcomes like hypothermia and renal and cardiac dysfunction." (PMID 39768394, 2024). "Taken together, we show that a novel AQP9 inhibitor, RG100204 demonstrates the ability to prevent sepsis-induced multiple organ dysfunction." (PMID 35774785, 2022). "A novel AQP9 inhibitor, RG100204, was found to attenuate cardiac dysfunction as well as renal dysfunction and hepatocellular injury in a cecal ligation and puncture (CLP) model of sepsis." (PMID 39544938, 2024). "In contrast, AQP9 expression was not altered during sepsis and was correlated with neutrophil count, and low levels of AQP9 were associated with increased survival." (PMID 38279209, 2024). "AQP3 (p < 0.0001) expression more than doubled when comparing day 8 of sepsis with day 1, whereas AQP9 mRNA expression was not altered over the duration of sepsis." (PMID 38279209, 2024). "AQP9 has been recently demonstrated to have an important pathophysiological role in sepsis, since RG100204, a novel, potent and selective AQP9 inhibitor, reduced septic cardiomyopathy and multiple organ failure in a cecal ligation and puncture (CLP) induced murine model of polymicrobial infection." (PMID 35883453, 2022). "Interestingly, AQP3, AQP5, and AQP9 are critical in the immune system due to their role in immune cell migration, where AQP5 and AQP9 regulate neutrophil cell migration and impact sepsis survival." (PMID 36212456, 2022). "Furthermore, in cases of ICU-acquired sepsis and SIRS, there is a notable alteration in the expression of AQP1 and AQP9 in leukocytes, which may play a role in cellular responses and plasma membrane dynamics under inflammatory conditions." (PMID 39544938, 2024). "Therefore, our results may suggest an opposing role for AQP9 and other AQPs like AQP3 in sepsis." (PMID 38279209, 2024). "Moreover, AQP9 mRNA expression has been found to be elevated in human subjects injected with LPS as well as in a cohort of ARDS patients, while recent studies have demonstrated that inhibition of AQP9 expression may protect patients from sepsis-induced complications." (PMID 38203657, 2023).
Hepatic steatosis (15 papers, 2013 to 2024). Steatosis is a term used to denote lipid accumulation within hepatocytes. "Moreover, in male rats, 8 weeks of HFD was associated with an increased hepatic AQP9 abundance and knockdown of AQP9 was reported to alleviate the degree of hepatic steatosis." (PMID 33193093, 2020). "Thus, it seems plausible that the reduction of total and glycosylated AQP9 may be reflecting an increase in ER stress associated to fatty liver." (PMID 24205128, 2013). "Starved obese leptin-deficient (ob/ob) mice, a model of NAFLD, displayed deficient AQP9 expression and function and increased levels of plasma glycerol compared to lean mice, suggesting the implication of AQP9 in liver steatosis." (PMID 35883453, 2022). "Oleic acid treatment boosts the p38 phosphorylation, while the inhibition of p38 prevents AQP9 upregulation, suggesting AQP9 as an important player in oleic acid-induced hepatic steatosis in HepG2 cells via p38 signaling." (PMID 35883453, 2022). "As a result, insulin negatively regulates Aqp9 transcription, which explains why patients with insulin resistance are more likely to develop fatty liver disease, which can lead to CLI." (PMID 34659635, 2021). "TNF-α has been also reported to decrease the protein expression of another aquaglyceroporin, AQP9, in a hepatocyte model of fatty liver disease." (PMID 32512939, 2020). "Leire Méndez-Giménez found that sleeve gastrectomy, a widely applied bariatric surgery procedure, restores the coordinated regulation of fat-specific AQP7 and liver-specific AQP9, thereby improving whole-body adiposity and hepatic steatosis." (PMID 31275413, 2019). "AQP9 seems to be of minor pathophysiological relevance in the fatty liver disease of alcoholic origin." (PMID 30042691, 2018). "Adipose Aqp3 and hepatic Aqp9 transcripts positively correlated with markers of adiposity and hepatic steatosis." (PMID 26159457, 2015). "Further work is warranted to decipher the exact mechanism governing the down-regulation of AQP9 in hepatic steatosis." (PMID 24205128, 2013). "Functional involvement of AQP9 in liver steatosis is shown providing important insights into the knowledge of NAFLD pathogenesis, with a major translational value." (PMID 24205128, 2013). "Among that, PCK1-mediated phosphorylation of INSIG1/2 could promote the activation of SREBP1 lipogenesis, and AQP9 could facilitate the hepatic uptake of glycerol and knockdown of the AQP9, thereby reducing hepatic steatosis." (PMID 38665091, 2024). "Additionally, treatment with oleic acid increased p38 phosphorylation, and blocking p38 prevented AQP9 upregulation, suggesting that AQP9 contributes to oleic acid-induced hepatic steatosis in HepG2 cells through p38 signaling." (PMID 39596202, 2024). "Interestingly, hepatic AQP9 protein levels, the main hepatic glycerol AQP, are inversely associated with the severity of hepatic steatosis, suggesting glycerol homeostasis affects and/or is affected by liver steatosis." (PMID 35075822, 2022). "In summary, our results suggest implication of AQP9 in liver steatosis." (PMID 24205128, 2013). "Thus, despite the protective role of AQP9 against hepatic steatosis, the effect of a sustained reduction of AQP9 on the accumulation of ammonia in the liver cannot be discarded." (PMID 24205128, 2013). "However, we cannot exclude that during liver steatosis hepatocyte AQP9 undergoes to diverse mechanisms of dysregulation depending on the origin, pattern and extent of ectopic TG accumulation." (PMID 24205128, 2013). "Further studies are needed to verify this provocative hypothesis by evaluating the time course of hepatocyte AQP9 expression and glycerol permeability during the pathogenesis of liver steatosis." (PMID 24205128, 2013).
Hepatic steatosis (continued). "Regarding liver AQP9, inhibition of AQP9-facilitated glycerol import by hepatocytes may be effective in the prevention of liver steatosis and some of its severe consequences, such as steatohepatitis and cirrhosis, or in the control of gluconeogenesis from glycerol in T2D." (PMID 27409609, 2016). "Aqp9 gene expression was positively associated with markers of adiposity [body weight (r = 0.60, P < 0.001) or subcutaneous WAT/body weight (r = 0.44, P = 0.002)] and hepatic steatosis [liver/body weight (r = 0.69, P < 0.001) and intrahepatic TG (r = 0.28, P < 0.05)]." (PMID 26159457, 2015). "Moreover, AQP9 expression in the liver might influence and/or might be influenced by ongoing liver steatosis." (PMID 24205128, 2013). "Importantly, the AQP9 diminution paralleled the degree of hepatic steatosis, an observation that corroborated the notion that lower intrahepatocellular glycerol due to a decreased AQP9 expression may represent a compensatory mechanism to reduce the de novo TAG synthesis in fatty hepatocytes." (PMID 26594198, 2015). "In conclusion, Qutanhuoxue decoction can reduce the degree of hepatic steatosis, which may be closely related to the increase of AQP7 expression in adipose tissue and the decrease of AQP9 expression in liver." (PMID 31275413, 2019). "Exposure to ethanol, in spite of not changing AQP9 expression, increased the activity of GK and PEPCK (phosphoenolpyruvate carboxykinase), leading to increased production of G3P, which thereby could contribute to alcoholic hepatic steatosis." (PMID 30042691, 2018). "A reduction of hepatocyte AQP9 protein with no changes in transcript level was recently observed in n3-PUFA (ω3 polyunsaturated fatty acids)-depleted female rats, a model of metabolic syndrome displaying several features of the disease also including liver steatosis." (PMID 24205128, 2013).